TACC2 (transforming acidic coiled-coil containing protein 2)
Diseases named in the same sentence as TACC2 in open-access papers (continued):
Sharing a sentence is not in itself a finding about the gene and the disease.
cancer (14 papers, 2005 to 2025). A tumor composed of atypical neoplastic, often pleomorphic cells that invade other tissues. "High TACC2 expression found in human cancers, including breast cancer, hepatocellular carcinoma, and prostate cancer, is correlated with poor prognosis, suggesting its tumor-promoting potential." (PMID 35906197, 2022). "We employed immunostaining of TACC2 protein and found its signal mainly in cancer cells, particularly their nucleus." (PMID 29074988, 2017). "The second locus (rs192386132; p = 2.80 × 10−8) is near TACC2, which encodes a transforming acidic coiled-coil containing protein that has been linked to cancer; no previous GWAS associations have been reported near (± 50kb) this locus." (PMID 31560688, 2019). "The exclusion of exon 3 in TACC2 may require additional features such as interaction with other RBPs, formation of mRNP complex or cancer specific signaling cascades." (PMID 26498364, 2015). "Similarly, loss of chromosome 10, in particular the region of chromosome 10q25-26 flanked by the DNA markers D10S221 to D10S216, which encompasses the TACC2 locus, is a frequent occurrence in cancers of different origins." (PMID 15918899, 2005). "FGFR2 fusion partners were several common genes such as BICC1 and TACC2, which are frequently detected in the biliary tract, while FGFR2 fusion partners of the other cancers were different from these common partner genes." (PMID 41226813, 2025). "Consistent with the literature, the results of the present study showed fusion of the FGFR2 gene with nine different partners, namely, TACC2, BICC1, BTBD16, WAC, HFM1, HOOK1, INPP5F, C10orf90, and WDR11, in five different types of cancer." (PMID 35342406, 2022). "The genes validated in this study – PTGS2, IL8, IL23A, TACC2 and PI3 – were selected based upon their differential response to treatment and their implication for cancer initiation." (PMID 24848801, 2014). "Given the importance of dysregulation of DNA damage repair and cell cycle checkpoints as cancer hallmarks, it is plausible that FBXL7 might regulate tumorigenesis by targeting TACC2 for degradation." (PMID 35906197, 2022). "The three human TACC proteins, TACC1, TACC2, and TACC3, are core components of the centrosome and have non-overlapping functions in the normal cell and the cancer cell." (PMID 21113414, 2010).
infection (2 papers, 2020 to 2022). The state of being infected such as from the introduction of a foreign agent such as serum, vaccine, antigenic substance or organism. "In response to infection, in male mice, the TACC2, BUB1B, ATP5MC3, and MYO1E, and in female mice, the CAP1, MRPL2, COX5A, KLHL21, PDIA6, TSPO, and USP14 had direct interaction with TP-53." (PMID 35844510, 2022). "We found collectively among SP-A variants several genes such as AKT1, BTK, CCL9, PPARG, and RELA to exhibit higher expression in females, whereas, CFLAR, C1QC, LSP1, CKAP2, KAT2B, TACC2, and RCC2 exhibited higher expression in males after infection." (PMID 32670284, 2020). "However, in response to infection, male mice exhibited higher expression levels of CFLAR, and FKBP5 (KO, 1A3), AKT1, and CCL9 (1A3, 6A2), C1QC (6A2), LSP1 (1A3, 6A2, and 6A4), CKAP2, and KAT2B (KO), TACC2 (1A0), RCC2 (1A3, 6A2), PPARG (1A3, 6A4), and ERP44 (6A2) compared to females." (PMID 32670284, 2020).
TACC2 also shares sentences with these, for which no sentence is quoted: glioblastoma (3 papers); lung carcinoma (2); seminoma (2); acute lymphoblastic leukemia (1); Alzheimer disease (1); cervical cancer (1); colon cancer (1); colorectal cancer (1); emphysema (1); esophageal squamous cell carcinoma (1); head and neck carcinoma (1); head and neck squamous cell carcinoma (1); hepatocellular carcinoma (1); inflammation (1); intrahepatic cholangiocarcinoma (1); leprosy (1); liver cancer (1); mixed germ cell tumor (1); mucinous adenocarcinoma (1); mucinous stomach adenocarcinoma (1); Opioid dependence (1); pancreatic cancer (1); prostate adenocarcinoma (1); rhabdomyosarcoma (1); sinonasal carcinoma (1); type 2 diabetes (1); uterine cancer (1).